SERPINA1 (serpin family A member 1)
Diseases named in the same sentence as SERPINA1 in open-access papers (continued):
Sharing a sentence is not in itself a finding about the gene and the disease.
autism (3 papers, 2009 to 2019). Persistent deficits in social interaction and communication and interaction as well as a markedly restricted repertoire of activity and interest as well as repetitive patterns of behavior. "Besides, three proteins i.e., A2M, SERPINA1, and SERPIND1 were also associated with complement and coagulation cascades in the present study, indicating that complement system and coagulation cascades may be involved in the pathogenesis of autism." (PMID 30941018, 2019).
cognitive decline (3 papers, 2016 to 2022). "As all our PD patients undergo a clinical follow up to be able to redefine the diagnosis longitudinally, the CSF serpinA1 levels of patients developing a cognitive decline over the years can be checked immediately." (PMID 27184740, 2016). "The bioinformatics data together indicate that upregulation of SERPINA1, VCP, PRNP, CIP2A, HSPA9, and UQCRC2 and downregulation of IGFBP3, CRHBP, PEPD, and GUSB were correlated to cognitive decline in T2DM patients." (PMID 36506101, 2022).
colon adenocarcinoma (3 papers, 2020 to 2025). "However, others have reported that SERPINA1 may act as a protective factor in CRC, with its downregulation linked to the recurrence and distant metastasis of colon adenocarcinoma." (PMID 41425595, 2025).
cutaneous squamous cell carcinoma (3 papers, 2019 to 2021). "Among the members of the serpin family, SERPINA1 was suggested as a biomarker for gastric and cutaneous squamous cell carcinoma harboring tumor invasion and migration with poor prognosis." (PMID 32503295, 2020).
endometrial cancer (3 papers, 2022 to 2025). Primary or metastatic malignant neoplasm involving the endometrium (mucous membrane that lines the endometrial cavity). "HSPE1, SERPINA1 and PKM2 constitute the panel of proteins that satisfactorily differentiate endometrial cancer and normal endometrium." (PMID 39194522, 2024). "In endometrial cancer patients, the expression of ABCG, ATR, CLU, and LRG1 was upregulated, while the expression of SERPINA1 and KNG1 was downregulated." (PMID 39194522, 2024).
esophageal cancer (3 papers, 2017 to 2023). A primary or metastatic malignant neoplasm involving the esophagus. "In comparison, higher SERPINA1 expression was associated with poorer OS in ESCA (esophageal carcinoma), TGCT (testicular germ cell tumors), and THYM." (PMID 37511325, 2023).
gallstones (3 papers, 2017 to 2021). Solid crystalline precipitates in the biliary tract, usually formed in the gallbladder, resulting in the condition of cholelithiasis. "Among these, the levels of serum SERPINA1 and fucosylated SERPINA1 (fuco-SERPINA1) in PC patients were significantly higher than those in gallstone patients." (PMID 34707986, 2021).
head and neck cancer (3 papers, 2014 to 2023). A primary or metastatic malignant neoplasm affecting the head and neck. "In addition, serpins were associated with head and neck cancer; in particular, it has been reported that SERPINA1 is associated with tumor progression, while SERPINC1 and SERPINF2 are correlated with a good response to radiotherapy, and these data are in good agreement with our results." (PMID 37371031, 2023). "As shown, NNMT, FLI1, SLPI, LAMP3, SERPINA1, GAS6, and CD274 have been often used as biomarkers for OSCC or head and neck cancer, while other genes listed have seldom been investigated in oral cancer and may be considered as novel biomarkers for OSCC prevalence and treatment." (PMID 28286742, 2017).
mastitis (3 papers, 2014 to 2020). Inflammation of breast tissue during lactation or postpartum due to an obstructed duct or infection. "Concomitantly with the early induction of cytokine and chemokine-encoding genes, we identified an up-regulation of two genes coding for acute phase proteins (APP): pentraxin 3 (PTX3) and α-1 anti-proteinase (SERPINA1) which were also found in bovine milk at the beginning of mastitis." (PMID 24521038, 2014).
migraine (3 papers, 2021 to 2023). "ANKDD1B and SERPINA1 were the nearest genes to a genome-wide significant migraine risk SNP, and POC5 was the nearest gene to a genome-wide significant T2D risk SNP." (PMID 36292730, 2022). "Additionally, regions at chromosomes 14 and 17 contain the SERPINA1 and SMG6 genes, which were previously shown to be the closest genes to a lead migraine SNP." (PMID 36808568, 2023).
oral squamous cell carcinoma (3 papers, 2023 to 2025). "Potential salivary diagnostic indicators for oral squamous carcinoma include higher salivary levels of SERPINA1 in individuals with oral squamous cell carcinoma, which correspond with advanced tumor stage." (PMID 40661938, 2025).
protein misfolding diseases (3 papers, 2019 to 2025). "On the one hand, these findings may indicate common pathological pathways involving serpinA1 in different proteinopathies." (PMID 35805926, 2022).
squamous cell carcinoma (3 papers, 2012 to 2024). A carcinoma arising from squamous epithelial cells. "Moreover, a significant increase in squamous cell carcinoma proteins marker genes such as SerpinA1, SerpinA3 and EphB2 under the influence of UV radiation was observed in cells with efficiently functioning NLRP1 and NLRP3." (PMID 39839625, 2024).
acute coronary syndrome (2 papers, 2021 to 2023). Signs and symptoms related to acute ischemia of the myocardium secondary to coronary artery disease. "The authors concluded that hypermethylation of SERPINA1 may represent a potential biomarker for predicting COPD development in acute coronary syndrome patients." (PMID 36902496, 2023).
Breast Invasive Carcinoma (2 papers, 2023 to 2024). "In the “Breast Invasive Carcinoma of TCGA—PanCancer Atlas” study, SERPINA1 was observed to have mutations in approximately 2% of the samples profiled for this gene (996 in total)." (PMID 39851465, 2024). "In the “Breast Invasive Carcinoma of TCGA—PanCancer Atlas” study, mutations in SERPINA1 were identified in approximately 2% of the samples analyzed, including variants of uncertain significance." (PMID 39851465, 2024).
colorectal adenocarcinoma (2 papers, 2021 to 2022). The most common type of colorectal carcinoma. "SERPINA1 was a participant in the progression of colorectal adenocarcinoma." (PMID 34925026, 2021).
common variable immunodeficiency (2 papers, 2024 to 2025). "In this context, we analyzed 80 PAD patients, including 70 with common variable immunodeficiency (CVID) for SERPINA1 defects, in order to investigate the possible contribution to PAD clinical phenotype." (PMID 38791420, 2024).
corneal ulcer (2 papers, 2013 to 2024). Area of epithelial tissue loss from corneal surface; associated with inflammatory cells in the cornea and anterior chamber. "The level of SERPINA1 in tear fluid have been reported to be increased in patients with corneal ulcers, conjunctival diseases and after continuous contact lens wear." (PMID 38368345, 2024).
disc degeneration (2 papers, 2021 to 2023). "Therefore, SERPINA1 can be used as a biomarker to regulate or predict the progress of disc degeneration." (PMID 37009470, 2023).
endothelial dysfunction (2 papers, 2020 to 2025). In vascular diseases, endothelial dysfunction is a systemic pathological state of the endothelium (the inner lining of blood vessels) and can be broadly defined as an imbalance between vasodilating and vasoconstricting substances produced by (or acting on) the endothelium. "Specifically, GLUL may contribute to CHD through its involvement in glutamate metabolism and endothelial dysfunction, while SERPINA1 appears to be linked to protease inhibition and inflammation modulation." (PMID 41287052, 2025).
generalized pustular psoriasis (2 papers, 2024). A rare and extreme form of psoriasis characterized by the appearance of sterile pustules which can take many patterns. "The mutations in both SerpinA1 and SerpinA3 are likely to be predisposing risk factors of generalized pustular psoriasis (GPP)." (PMID 39737188, 2024). "Other genes with mutations identified in patients with generalized pustular psoriasis include the adaptor-related protein complex 1 subunit sigma 3 (AP1S3), mutations in Myeloperoxidase (MPO) genes, Serpin Family A Member 1 (SERPINA1) and SERPINA3, TNIP1, and IL1RN." (PMID 38256115, 2024).
Huntington disease (2 papers, 2013 to 2021). Huntington disease (HD) is a rare neurodegenerative disorder of the central nervous system characterized by unwanted choreatic movements, behavioral and psychiatric disturbances and dementia. "Antagonizing the pathogenic overexpression of SERPINA1 in neurons and glia mitigates mutant Huntingtin (mHTT)-induced behavioral impairments and lowers mHTT protein levels in Drosophila and Huntington's disease (HD) mouse striatal cells." (PMID 33871358, 2021).
infiltrating ductal breast carcinoma (2 papers, 2016 to 2024). "In a bioinformatic analysis of invasive ductal carcinoma, SERPINA1 was identified as a prognostically significant gene, participating in and establishing an effective prognostic model." (PMID 38710698, 2024).
iron overload (2 papers, 2016 to 2021). "We also found exonic non-synonymous variants in BMP6, HP and Serpina1, whose proteins might act as possible modulators of hepcidin synthesis and iron overload." (PMID 33513852, 2021).
medulloblastoma (2 papers, 2020 to 2024). A malignant, invasive embryonal neoplasm arising from the cerebellum. "Despite the batch correction, certain proteins, like SERPINA1 in ALL patients and CKB in medulloblastoma patients, showed consistent trends across both the original and corrected data." (PMID 38350915, 2024).
multiple myeloma (2 papers, 2021 to 2025). "To examine potential glycosylation on SERPINA1, we treated plasma proteins obtained from PC patients and a commercially available recombinant human SERPINA1 protein (derived from a mouse myeloma cell line NS0) with PNGase F to eliminate glycan." (PMID 34199928, 2021).
ovarian tumor (2 papers, 2010 to 2018). "The significance of APOC2, APOC4, ORM1, SERPINA1, and SERPINA10 in differential diagnosis of ovarian tumors was not confirmed." (PMID 30065196, 2018).
papillary thyroid carcinoma (2 papers, 2011 to 2023). "SERPINA1 has been reported before as a potential diagnostic marker for papillary thyroid carcinoma in a study investigating its protein expression in thyroid biopsy tissue by Immunocytochemistry and Western Blot." (PMID 21470421, 2011). "In the independent validation RT-qPCR data, where we picked samples from all histological entities, the papillary carcinomas again show a distinctly elevated expression of SERPINA1 compared to all other histological groups under investigation." (PMID 21470421, 2011). "From meta analysis we identified one gene (SERPINA1) which identifies papillary thyroid carcinoma against benign nodules with 99% accuracy (n = 99, sensitivity = 0.98, specificity = 1, PPV = 1, NPV = 0.98)." (PMID 21470421, 2011).
psoriasis (2 papers, 2022 to 2024). An autoimmune condition characterized by red, well-delineated plaques with silvery scales that are usually on the extensor surfaces and scalp. "The inhibitory capacity of SerpinA1 is reduced in symptom-free and in those with stationary lesions patients with psoriasis." (PMID 39737188, 2024). "Clinical studies have confirmed that the concentration of SerpinA1 in the serum of psoriasis patients with different stages of pathological characteristics has changed, and the expression of various isoenzymes of SerpinA1 was also found in these patients." (PMID 36148224, 2022).
pterygium (2 papers, 2014 to 2025). A wedge-shaped fibrovascular lesion arising from the bulbar conjunctiva and extending to the cornea. "SERPINA1 and transferrin (TF) were down-regulated at both protein and transcript levels in pterygium." (PMID 24825356, 2014).
ulcer (2 papers, 2022 to 2023). "Diabetic wounds have increased elastase associated with infection and worsening of ulcers, consistent with our observation of decreased levels of the SerpinA1/α1PI elastase inhibitor in diabetic wound EVs." (PMID 36335351, 2022).
varicocele (2 papers, 2020). A condition characterized by the dilated tortuous veins of the spermatic cord with a marked left-sided predominance. "Another protein typically under-expressed in patients with varicocele is alpha-1-antitrypsin (SERPINA1), involved in the inhibition of proteases implicated in stimulating the inflammatory response." (PMID 33266209, 2020).
adenomyosis (1 paper, 2025). The growth of endometrial tissue inside the muscular wall of the uterine corpus. "On comparing adenomyosis patients with controls, significant differences were observed in the expression of MMP9, MMP11, SERPINA1, IGFBP5, and TIMP1 (p < 0.05); however, MMP7 and THBS1 remained comparable." (PMID 41272701, 2025).
astrocytomas (1 paper, 2022). "Interestingly both FCGBP and SERPINA1 have been proposed as GB-associated genes due to their upregulation in primary and secondary GBs compared to lower-grade astrocytomas." (PMID 35052804, 2022).
autosomal recessive deafness 1A (1 paper, 2025). "The GJB2 (autosomal recessive deafness 1A) and SERPINA1 (alpha-1-antitrypsin deficiency) genes harbored the second highest carrier frequency of P/LP variants in the study cohort (5.5%)." (PMID 41595422, 2025).
cardiac amyloidosis (1 paper, 2025). Cardiac amyloidosis is a condition whereby cardiac tissue is infiltrated by amyloid fibrils. "SERPINA1 reduces the risk of cardiac amyloidosis by inhibiting plasmin-mediated transthyretin hydrolysis and aggregation; it modulates the Eph receptor B2 signaling pathway to improve energy metabolism and glucose homeostasis, thereby influencing cardiometabolic diseases." (PMID 41287052, 2025).
cervical squamous cell carcinoma (1 paper, 2023). A squamous cell carcinoma arising from the cervical epithelium. "In the Kaplan–Meier plotter database, higher SERPINA1 expression was connected to better OS in CESC (cervical squamous cell carcinoma and endocervical adenocarcinoma), THCA, and UCEC." (PMID 37511325, 2023).
Cognitive impairment (1 paper, 2016). Abnormal cognition is characterized by deficits in thinking, reasoning, or remembering. "We propose this serpinA1 CIEF-immunoassay as a novel tool in predicting cognitive impairment in PD patients and therefore for patient stratification in therapeutic trials." (PMID 27184740, 2016). "This hypothesis is supported by the finding that PD patients suffering from mild cognitive impairment showed elevated serpinA1 peak 0 levels compared to PD patients without MCI." (PMID 27184740, 2016).
Down and Edwards syndromes (1 paper, 2025). "While these specific serpins have not been directly linked to fetal aneuploidy, other family members, such as SERPINA3 and SERPINA1, have been reported as dysregulated in Down and Edwards syndromes." (PMID 41614738, 2025).
HCMV infection (1 paper, 2020). "In particular, HCMV infection led mainly to the over-expression of CCL2, CCL3, CCL11, CXCR4, IL-1β, IL13, MMP1, MMP3, MMP9 and MMP13, SERPINA1, TNFα, and BMP7, and the gradual and constant downregulation of IL13RA2 (up to almost 800-fold at 14 days p.i.)." (PMID 32899126, 2020).
hyperthyroidism (1 paper, 2023). Overactivity of the thyroid gland resulting in overproduction of thyroid hormone and increased metabolic rate. "SERPINA1, a protein associated with inflammatory disease, organismal injury, and abnormal thyroid function, is significantly lower in hyperthyroidism samples than in normal thyroid samples." (PMID 37324256, 2023).
hypogonadism (1 paper, 2025). A disorder characterized by decreased function of the gonads. "Protein-coding variants in several liver genes, such as PNPLA3, GCKR, SLCO1B1, SERPINA1, HGFAC, and UGT2B15, were significantly associated with total testosterone levels and hypogonadism risk." (PMID 40316537, 2025).
intrahepatic cholestasis (1 paper, 2021). A cholestasis characterized by impairment of the bile flow caused by obstruction located in the liver. "The prevalence of SERPINA1 PI*Z variant in a group of women with intrahepatic cholestasis is higher compared to general population." (PMID 34557220, 2021). "Given the link between the deficient variants of the SERPINA1 gene and pediatric intrahepatic cholestasis as a manifestation of AATD, we aimed to assess the presence and frequency of the two most common SERPINA1 nucleotide variants – PI*Z and PI*S – in a group of 103 women with a history of ICP." (PMID 34557220, 2021).
juvenile idiopathic arthritis (1 paper, 2022). Juvenile idiopathic arthritis (JIA) is the term used to describe a group of inflammatory articular disorders of unknown cause that begin before the age of 16 and last over 6 weeks. "Here, we characterized a large family of 5 patients with juvenile idiopathic arthritis and psoriatic features who harbor pathogenic variants in the SERPINA1 gene." (PMID 35786784, 2022).
knee osteoarthritis (1 paper, 2021). "For example, rs76340814 (PTCH1) and rs28929474 (missense variant in SERPINA1) have stronger associations and larger effect sizes with total hip replacement (THR), total knee replacement (TKR), and total joint replacement (TJR), than with hip or knee osteoarthritis." (PMID 34450027, 2021).
large artery stroke (1 paper, 2019). Stroke caused by the blockage of blood flow in one of the large arteries feeding the brain. "Modification in SERPINA1 was diagnosed with development of large artery stroke, but this altered gene may be liable for progression of CAD." (PMID 31881747, 2019).
lipodystrophy (1 paper, 2024). A congenital or acquired disorder characterized by abnormal loss or redistribution of the adipose tissue in the body. "Here, we show that serine protease inhibitor A1 (SerpinA1) expression in the liver is increased during recovery from lipodystrophy caused by the adipocyte-specific loss of insulin signaling in mice." (PMID 39532838, 2024). "SerpinA1 knockout impaired the fat recovery potential in Ai-IRKO mice that developed tamoxifen-induced lipodystrophy 6 weeks after tamoxifen injection." (PMID 39532838, 2024).
Meconium ileus (1 paper, 2024). Obstruction of the intestine due to abnormally thick meconium. "Primary risk factors for CFLD development include male gender, a history of meconium ileus (with a fivefold higher risk), pancreatic insufficiency, particularly in patients with class I, II, or III mutations, CF-related diabetes (CFRD), and the SERPINA-1 allele." (PMID 38473009, 2024).
oropharyngeal squamous cell carcinoma (1 paper, 2024). "Aligning with this change, sialylated SERPINA1 were up-regulated in early-stage oropharyngeal squamous cell carcinoma and in metastatic HCC compared to non-metastatic HCC group, suggesting that sialylated SERPINA1 was closely associated with HCC." (PMID 38561745, 2024).
prion disease (1 paper, 2022). A transmissible disease that is caused by a protein that is able to induce abnormal folding of normal cellular proteins, leading to characteristic spongiform brain changes, which are associated with neuronal loss without an inflammatory response. "Moreover, additional specific alterations in FTLD and prion disease were observed only according to molecular subtypes, suggesting the specific involvement of individual misfolded proteins and/or strains in serpinA1 pathophysiology." (PMID 35805926, 2022).
progressive non-fluent aphasia (1 paper, 2018). Progressive non-fluent aphasia (PNFA) is a form of frontotemporal dementia (FTD), characterized by agrammatism, laborious speech, alexia, and agraphia, frequently accompanied by apraxia of speech (AOS). "In a recent gene-based association study, SERPINA1 was shown to be associated with progressive non-fluent aphasia (PNFA, a subtype of FTD), but not bvFTD." (PMID 30487733, 2018).
pustular psoriasis (1 paper, 2023). "Other genes involved in pustular psoriasis are SERPINA1 and SERPINA3 (serine protease inhibitors that inhibit cathepsin G, neutrophil elastase, and proteinase 3), TNIP1 and IL1RN." (PMID 37628670, 2023).